EMC10 (ER membrane protein complex subunit 10)
Description:
Part of the endoplasmic reticulum membrane protein complex (EMC) that enables the energy-independent insertion into endoplasmic reticulum membranes of newly synthesized membrane proteins. Preferentially accommodates proteins with transmembrane domains that are weakly hydrophobic or contain destabilizing features such as charged and aromatic residues. Involved in the cotranslational insertion of multi-pass membrane proteins in which stop-transfer membrane-anchor sequences become ER membrane spanning helices. It is also required for the post-translational insertion of tail-anchored/TA proteins in endoplasmic reticulum membranes. By mediating the proper cotranslational insertion of N-terminal transmembrane domains in an N-exo topology, with translocated N-terminus in the lumen of the ER, controls the topology of multi-pass membrane proteins like the G protein-coupled receptors. By regulating the insertion of various proteins in membranes, it is indirectly involved in many cellular processes (Probable). Promotes angiogenesis and tissue repair in the heart after myocardial infarction. Stimulates cardiac endothelial cell migration and outgrowth via the activation of p38 MAPK, PAK and MAPK2 signaling pathways.
Synonyms: C19orf63; INM02; HSS1; HSM1; NEDDFAS
Tractability: Small molecule: a structure with a bound ligand is known. Antibody: UniProt places it where antibodies can reach, with high confidence; its Gene Ontology location is reachable by antibodies, with high confidence; UniProt predicts a signal peptide or a membrane-spanning region. PROTAC: ubiquitination databases record sites on it.
Gene: Protein-coding gene on chromosome 19 (50,476,400 to 50,490,871, forward strand). Ensembl gene ENSG00000161671.
Subcellular location: Endoplasmic reticulum membrane (Isoform 1); Secreted (Isoform 2)
Gene Ontology:
Molecular function: membrane insertase activity
Biological process: positive regulation of angiogenesis; positive regulation of endothelial cell proliferation; protein insertion into ER membrane by stop-transfer membrane-anchor sequence; tail-anchored membrane protein insertion into ER membrane; positive regulation of endothelial cell migration
Cellular component: EMC complex; endoplasmic reticulum membrane; extracellular region; membrane
Genetic constraint (gnomAD): Loss-of-function variants: 32 observed, 26.72 expected, observed/expected ratio (o/e) 1.2, 90% interval 0.9 to 1.61. The synonymous counts are far from expectation, so gnomAD's model fits this gene poorly and the ratio says little. Missense variants: 357 observed, 278.39 expected, observed/expected ratio (o/e) 1.28, 90% interval 1.17 to 1.4. Synonymous variants: 157 observed, 123.63 expected, observed/expected ratio (o/e) 1.27, 90% interval 1.11 to 1.45.
Homologues: Orthologues: chimpanzee EMC10 (99% identical), macaque EMC10 (98% identical), dog EMC10 (92% identical), guinea pig EMC10 (91% identical), pig EMC10 (90% identical), mouse Emc10 (84% identical), rat Emc10 (75% identical), tropical clawed frog emc10 (60% identical), zebrafish emc10 (51% identical).
Diseases named in the same sentence as EMC10 in open-access papers:
EMC10 is named in the same sentence as 37 diseases in open-access papers, as found by Europe PMC text mining. Sharing a sentence is not in itself a finding about the gene and the disease. The quoted sentences say what the papers report.
Intellectual disability (4 papers, 2020 to 2025). "Variants in EMC10 have been related to neurodevelopmental disorders and intellectual disability, and alterations in LAMC3 have been linked to cortical development anomalies and epilepsy." (PMID 41009814, 2025). "Genome-wide linkage analysis to the phenotype of intellectual disability determined a maximum LOD score of 6.49 on chromosome 19, consistent with the location of EMC10." (PMID 33531666, 2021).
glioma (3 papers, 2014 to 2021). A benign or malignant brain and spinal cord tumor that arises from glial cells (astrocytes, oligodendrocytes, ependymal cells). "We note from the literature that the peptide glioma growth inhibitor hHSS1/C19orf63/EMC10 also upregulates PNLIPRP3 very highly in U87 cells." (PMID 34359681, 2021). "In an in vitro study, EMC10 was suggested as a potential therapeutic target for malignant glioblastoma after being found to exert cell proliferation inhibition, invasion, angiogenesis in endothelial cells, and cell migration in glioma cell lines." (PMID 32869858, 2020).
Insulin resistance (3 papers, 2022 to 2024). Increased resistance towards insulin, that is, diminished effectiveness of insulin in reducing blood glucose levels. "In summary, our data demonstrate that circulating EMC10 is positively correlated with BMI and insulin resistance in humans, and weight loss interventions reduce serum EMC10." (PMID 36443308, 2022). "Consistent with an association between serum EMC10 and insulin resistance, serum EMC10 levels correlated positively with fasting plasma glucose, HbA1c, free fatty acids (FFA) and leptin, and inversely with serum adiponectin." (PMID 36443308, 2022). "As obesity causes insulin resistance and cardiometabolic disease, we examined the association of serum EMC10 with insulin sensitivity and other cardiometabolic traits." (PMID 36443308, 2022). "Therefore, serum EMC10 is positively associated with BMI, fat mass, insulin resistance and adverse metabolic clinical biochemistry in humans." (PMID 36443308, 2022). "Conversely, Emc10 overexpression mice were more easily induced into obesity and insulin resistance on high-fat diets, had less adipocyte thermogenesis, and lower whole-body energy expenditure." (PMID 37680891, 2023). "The whole-body Emc10 knockout mice, displaying more adipocyte thermogenesis and higher whole-body energy expenditure, resisted obesity and insulin resistance induced by high-fat diets." (PMID 37680891, 2023).
Obesity (2 papers, 2022 to 2023). Accumulation of substantial excess body fat. "Our data demonstrate that loss of EMC10 enhances thermogenic capacity of adipocytes, increases energy expenditure and protects mice from diet-induced obesity." (PMID 36443308, 2022). "Taken together, our gain and loss of function experiments in mice demonstrate that scEMC10 is a regulator of energy balance and provides supportive evidence that the associations between serum EMC10 and BMI observed in humans with obesity are causal." (PMID 36443308, 2022). "Taken together, our proof-of-concept study demonstrates that immunological neutralization of circulating EMC10 promotes weight loss and improves obesity-induced metabolic dysfunction in obese B6 mice." (PMID 36443308, 2022). "Consistent with a causal role for scEMC10 in obesity, Emc10-/- mice are resistant to diet-induced obesity due to an increase in energy expenditure, while scEMC10 overexpression decreases energy expenditure, thus promoting obesity in mouse." (PMID 36443308, 2022). "We reasoned that the association of serum EMC10 with increasing BMI and fat mass could be a primary cause of increased adiposity or a consequence, partially mediating the metabolic complications of obesity." (PMID 36443308, 2022). "Given that human tissue is limited, we analyzed scEmc10 abundance across various metabolic tissues from lean and obese mice to help inform the source of circulating EMC10 in obesity." (PMID 36443308, 2022). "Consistent with the chow diet data, we observed that increased circulating EMC10 promotes diet-induced obesity in mice as early as two weeks after introduction of HFD." (PMID 36443308, 2022). "Consistent with a role in the pathogenesis of human obesity, circulating EMC10 exhibits striking positive correlations with indices of adiposity in humans." (PMID 36443308, 2022). "Taken together, our data indicate that increased thermogenesis in the Emc10 KO mice is the primary mechanism contributing to their resistance to diet-induced obesity." (PMID 36443308, 2022). "The motivation of our mouse studies was to characterize the role of scEMC10 in the pathophysiological context of obesity, given the striking correlations between adiposity and circulating EMC10 observed in our observational studies in humans." (PMID 36443308, 2022). "Similar to findings in the white cohort, serum EMC10 levels were higher in human study participants with overweight and obesity than lean controls in a Chinese Han cohort." (PMID 36443308, 2022). "Here the authors show that scEMC10 is upregulated in people with obesity, and that that genetic EMC10 deletion or antibody-based neutralization of EMC10 prevents diet-induced obesity in mice." (PMID 36443308, 2022). "In summary, Emc10 KO protects mice from diet induced obesity." (PMID 36443308, 2022).
22q11.2 deletion syndrome (1 paper, 2025). 22q11.2 deletion syndrome (DS) is a chromosomal anomaly which causes a congenital malformation disorder whose common features include cardiac defects, palatal anomalies, facial dysmorphism, developmental delay and immune deficiency. "However, further studies in mice have shown that a DNA deletion equivalent to the one in humans with 22q11.2 deletion syndrome leads to excessive production of EMC10 – suggesting that too much EMC10 can be harmful." (PMID 40420562, 2025).
asthenozoospermia (1 paper, 2022). "Together with the finding that in vitro incubation of recombinant scEMC10 could not improve motility of Emc10 KO spermatozoa, these results suggest that recombinant scEMC10 has limited therapeutic value for patients with asthenospermia." (PMID 36077468, 2022). "Furthermore, we observed a positive correlation between EMC10 and ATP1B3 in human sperm, while no application value was confirmed for scEMC10 in the diagnosis and treatment of asthenospermia." (PMID 36077468, 2022).
autoimmune disease (1 paper, 2018). A disorder resulting from loss of function or tissue destruction of an organ or multiple organs, arising from humoral or cellular immune responses of the individual to their own tissue constituents. "Importantly, EMC10 has been consistently associated to the autoimmune disease primary biliary cirrhosis." (PMID 29884787, 2018).
Cerebral atrophy (1 paper, 2021). Atrophy (wasting, decrease in size of cells or tissue) affecting the cerebrum. "Individuals with EMC10 variants had higher rates of seizures compared to EMC1, and individuals with EMC1 variants had cerebellar or cerebral atrophy that was not seen in the EMC10 cohort." (PMID 33531666, 2021).
cognitive deficits (1 paper, 2025). "However, whether similar beneficial effects could be achieved in human neurons and whether Emc10 normalization in the adult brain could reverse established cognitive deficits remained unknown." (PMID 40420562, 2025).
Dysarthria (1 paper, 2022). Dysarthric speech is a general description referring to a neurological speech disorder characterized by poor articulation. "In contrast, expanding the clinical spectrum of the EMC10‐related NDD, the cases reported here presented with dysarthria, persistent peripheral hypotonia, movement disorders, gait ataxia, and vermian atrophy together with noticeable growth impairment, and hyperparathyroidism." (PMID 35684946, 2022).
Glucose intolerance (1 paper, 2025). Glucose intolerance (GI) can be defined as dysglycemia that comprises both prediabetes and diabetes. "We have shown that Emc10 KO improves diet-induced glucose intolerance in mice." (PMID 40441535, 2025).
lupus erythematosus (1 paper, 2025). An autoimmune, connective tissue chronic inflammatory disorder affecting the skin, joints, kidneys, lungs, heart, and the peripheral blood cells. "For instance, FAM71E1 and EMC10 have been associated with lupus erythematosus and genes like PGA3, VWCE, and PTOV1 are associated with immune infiltrates and immunity in various tumors." (PMID 41009814, 2025).
male infertility (1 paper, 2022). The inability of the male to effect fertilization of an ovum after a specified period of unprotected intercourse. "In a previous study, we successfully established an Emc10 knockout (KO) mouse model and observed that EMC10 deficiency resulted in male infertility." (PMID 36077468, 2022). "Its deficiency contributes to male infertility and multiple sperm dysfunctions, including low sperm motility and high intracellular sodium concentration, similar to the phenotype of Emc10 KO mouse, while overexpression of ATP1A4 in transgenic mice significantly increased sperm motility." (PMID 36077468, 2022). "We previously reported that Emc10 knockout (KO) leads to mouse male infertility." (PMID 36077468, 2022).
schizophrenia (1 paper, 2020). A major psychotic disorder characterized by abnormalities in the perception or expression of reality. "In schizophrenia mouse models, reduced Mirta22 (human EMC10 ortholog) levels completely rescued the dendritic deficits and spine formation at the hippocampal pyramidal neurons, thus suggesting a key role in neuronal dendrites and spine development." (PMID 32869858, 2020).
steatosis (1 paper, 2022). Increased lipid within the cytoplasm of cells. "We observed Emc10 KO protected from steatosis caused by HFD." (PMID 36443308, 2022).
virus infection (1 paper, 2016). "In fact, our data suggest that other EMC subunits, particularly EMC3, EMC4, EMC5, EMC6, EMC7, and EMC10, may also exert roles in supporting virus infection." (PMID 28012275, 2016).
neurodevelopmental disorder (4 papers, 2020 to 2025). A behavioral and cognitive disorder with onset during the developmental period that involves impaired or aberrant development of intellectual, motor, or social functions. "Two biallelic variants in EMC10 have previously been associated with a neurodevelopmental disorder." (PMID 35684946, 2022). "Our work provides evidence that homozygous variants in EMC10 may lead to neurodevelopmental disorders in humans." (PMID 32869858, 2020).
cancer (1 paper, 2022). A tumor composed of atypical neoplastic, often pleomorphic cells that invade other tissues. "Work is ongoing to characterize circulating EMC10 concentrations in patients with cancer with and without cachexia." (PMID 36443308, 2022).
EMC10 also shares sentences with these, for which no sentence is quoted: developmental delay (2 papers); breast carcinoma (1); Cerebellar atrophy (1); epilepsy (1); fracture (1); Gait ataxia (1); genetic disorders (1); glioblastoma (1); Hip dysplasia (1); hyperparathyroidism (1); infection (1); movement disorder (1); myocardial infarction (1); nephrocalcinosis (1); osteoporosis (1); sarcoma (1); speech delay (1); synovial sarcoma (1); tumor (1).